SOCS4 (suppressor of cytokine signaling 4)
Description:
SOCS family proteins form part of a classical negative feedback system that regulates cytokine signal transduction. Substrate-recognition component of a SCF-like ECS (Elongin BC-CUL2/5-SOCS-box protein) E3 ubiquitin-protein ligase complex which mediates the ubiquitination and subsequent proteasomal degradation of target proteins. Inhibits EGF signaling by mediating the degradation of the Tyr-phosphorylated EGF receptor/EGFR.
Synonyms: SOCS7
Tractability: PROTAC: ubiquitination databases record sites on it.
Gene: Protein-coding gene on chromosome 14 (55,027,120 to 55,049,489, forward strand). Ensembl gene ENSG00000180008.
Subcellular location (Human Protein Atlas): Cytosol; Nucleoplasm
Pathways (Reactome):
Gene expression (Transcription): RUNX1 regulates transcription of genes involved in differentiation of keratinocytes
Gene Ontology:
Molecular function: protein binding
Biological process: negative regulation of epidermal growth factor-activated receptor activity; cytokine-mediated signaling pathway; intracellular signal transduction; positive regulation of proteasomal ubiquitin-dependent protein catabolic process; protein ubiquitination
Genetic constraint (gnomAD): Loss-of-function variants: 20 observed, 35.56 expected, observed/expected ratio (o/e) 0.56, 90% interval 0.4 to 0.82. The upper end of that interval is the gene's LOEUF score, 0.82, which puts it in group 3 of 6, group 1 being the genes least tolerant of losing a copy. Missense variants: 471 observed, 554.35 expected, observed/expected ratio (o/e) 0.85, 90% interval 0.79 to 0.92. Synonymous variants: 179 observed, 195.34 expected, observed/expected ratio (o/e) 0.92, 90% interval 0.81 to 1.04.
Homologues: Orthologues: chimpanzee SOCS4 (99% identical), dog SOCS4 (93% identical), pig SOCS4 (93% identical), rabbit SOCS4 (93% identical), mouse Socs4 (86% identical), rat Socs4 (85% identical), guinea pig SOCS4 (80% identical), tropical clawed frog socs4 (72% identical), zebrafish socs4 (39% identical), Drosophila melanogaster Socs36E (34% identical), Drosophila melanogaster Socs44A (16% identical), zebrafish socs1b (10% identical). Paralogues in human: SOCS5 (52% identical), SOCS6 (21% identical), SOCS7 (20% identical), CISH (13% identical), SOCS2 (12% identical), SOCS3 (10% identical), SOCS1 (10% identical).
Diseases named in the same sentence as SOCS4 in open-access papers:
SOCS4 is named in the same sentence as 26 diseases in open-access papers, as found by Europe PMC text mining. Sharing a sentence is not in itself a finding about the gene and the disease. The quoted sentences say what the papers report.
breast carcinoma (10 papers, 2010 to 2022). "SOCS4 was previously shown to be associated with earlier tumor stage and better clinical prognosis in breast cancer." (PMID 35723400, 2022). "High expression of SOCS4 is significantly associated with an earlier tumor stage and a better clinical outcome in human breast cancer." (PMID 26437444, 2015). "Indeed, SOCS4 was previously shown to be inversely associated with tumor node metastasis in breast cancer, and another research found that SOCS4 was attenuated in gastric cancer tissues and SOCS4 hypermethylation was related to poor prognosis." (PMID 29552286, 2018). "In the view of previous studies which explain functional importance of SOCS4 and results of present study, it might be assumed that rs1952438 is associated with poorer prognosis of breast cancer by declining expression level of SOCS4." (PMID 25075970, 2014). "Higher expression levels of SOCS1, SOCS3, SOCS4, and SOCS7 have all been reported to associate with better prognosis in human breast cancer." (PMID 33758600, 2021). "In our study, high expression of SOCS4 was also associated with longer OS and RFS times in breast cancer patients." (PMID 34120621, 2021). "In conclusion, our study found that common variants in the SOCS4, TSLP and HGF genes might be related with breast cancer prognosis in Korean women." (PMID 25075970, 2014). "Similar mechanism may well be existent for SOCS1 and SOCS4-7 gene control in breast cancer and this will need further investigation." (PMID 20433750, 2010). "In this study, we found that the rs1952438 in the suppressors of cytokine signaling (SOCS4) gene, rs2289278 in the thymic stromal lymphopoietin (TSLP) gene and rs2074724 in the hepatocyte growth factor (HGF) gene were highly associated with a poor prognosis of breast cancer." (PMID 25075970, 2014). "In an analysis of 1109 breast cancer samples and 113 normal breast samples, SOCS2 and SOCS3 showed lower expression levels in cancer tissues than in normal tissues, and patients with high expression of SOCS2, SOCS3 and SOCS4 exhibited better outcome." (PMID 35884417, 2022). "In breast cancer, we reported an inverse relationship between SOCS4 expression and tumor TNM stage and that higher SOCS4 expression might be a predictor of better overall survival." (PMID 24757565, 2014).
gastric cancer (6 papers, 2014 to 2021). A primary or metastatic malignant neoplasm involving the stomach. "Downregulation of SOCS4 expression corresponding to CpG islands hypermethylation of the SOCS4 was also found in gastric cancer." (PMID 34439155, 2021). "One study used a double combination array analysis to prove that SOCS4 is a novel gastric cancer suppressor gene." (PMID 26437444, 2015).
influenza (6 papers, 2014 to 2024). An acute viral infection of the respiratory tract, occurring in isolated cases, in epidemics, or in pandemics; it is caused by serologically different strains of viruses (influenzaviruses) designated A, B, and C, has a 3-day incubation period, and usually lasts for 3 to 10 days. "The authors developed a SOCS4-deficient mouse model, and identified SOCS4’s crucial role in the inflammatory response to pathogen infection, namely influenza." (PMID 39676878, 2024). "SOCS4 expression is also modulated by infection, and has also been shown to increase virus clearance and protect against severe cytokine storm during influenza infection." (PMID 35204004, 2022). "While SOCS4 plays a negative regulatory role in inflammatory responses to influenza, it appears to be a positive regulator of TCR signaling." (PMID 24809749, 2014). "Given the important role of other SOCS proteins in controlling the immune response, we have generated SOCS4-mutant mice and used a mouse influenza infection model to investigate the biological function of SOCS4." (PMID 24809749, 2014). "In summary, there is an increased net production of pro-inflammatory cytokines and chemokines, and while the initiating defect remains unclear, SOCS4 appears to have a classical role as a negative regulator of cytokine production and/or response in the innate immune reaction to influenza infection." (PMID 24809749, 2014).
thyroid cancer (6 papers, 2015 to 2022). "This study also demonstrated that the overexpression of miR-25 directly reduced the expression of its direct target suppressor of cytokine signaling 4 (SOCS4) leading to increased IL-23 expression in human thyroid cancer cell lines and tissue samples." (PMID 29765562, 2018). "A previous study demonstrates that IL–23 induces migration and invasion in thyroid cancer cells through the miR–25/SOCS4 signaling pathway." (PMID 27029486, 2016). "First, we demonstrated that IL–23 upregulated miR–25 expression as well as downregulated SOCS4 expression in thyroid cancer cell migration and invasion." (PMID 26437444, 2015). "In this study, we found that miR–25 promotes the migration and invasion of thyroid cancer cells by targeting SOCS4." (PMID 26437444, 2015). "Similar results were also obtained in wound healing assay.Taken together, these data suggest that miR–25 is the key component involved in IL-23-mediated thyroid cancer cell migration and invasion through the inhibition of SOCS4 expression." (PMID 26437444, 2015). "Since SOCS4 negatively regulates migration, we next analyzed the role of SOCS4 in the cell proliferation of thyroid cancer cells." (PMID 26437444, 2015). "In this study, we observed that the levels of SOCS4 are decreased in IL-23-induced migration and invasion of thyroid cancer cells." (PMID 26437444, 2015). "Further, we also showed that miR–25 promotes thyroid cancer cell migration and invasion by targeting SOCS4." (PMID 26437444, 2015). "We further demonstrate that IL–23 regulates the migration and invasion of thyroid cancer cells via a miR–25/SOCS4 signaling pathway." (PMID 26437444, 2015). "The effect of the miR–25/SOCS4 signaling pathway on the migration of thyroid cancer cells was further evaluated using the miR–25 inhibitor." (PMID 26437444, 2015). "In summary, our present study provides a novel evidence indicating that miR–25 and SOCS4 play a functional role in regulating IL-23-mediated migration and invasion in thyroid cancer cells." (PMID 26437444, 2015). "Together, our data suggest that IL–23 induces migration and invasion in thyroid cancer cells by mediating the miR–25/SOCS4 signaling pathway." (PMID 26437444, 2015). "A recent study also reported that the expression of SOCS4 was decreased in thyroid cancer cells." (PMID 34120621, 2021). "Since miR–25 can suppress SOCS4 expression by sequence-specific binding to its 3′-UTR, we hypothesized that miR–25 may affect the migration and invasion of thyroid cancer via SOCS4." (PMID 26437444, 2015). "To determine whether SOCS4 participates in the IL-23-mediated migration and invasion of thyroid cancer cells, we constructed 4 human SOCS4-specific short hairpin RNA (shRNA)." (PMID 26437444, 2015). "Treatment with IL–23 resulted in reduced expression levels of SOCS4 in thyroid cancer cells." (PMID 26437444, 2015). "A study on a thyroid cancer cell line has suggested that SOCS-4 has an inhibitory effect on migration and that inhibition of SOCS-4 by miR-25 could promote thyroid cancer cell migration." (PMID 28751715, 2017). "In addition, overexpression or Knockdown of SOCS4 and treatment with IL–23 could not affect the cell proliferation of thyroid cancer cells." (PMID 26437444, 2015).
lung adenocarcinoma (4 papers, 2018 to 2025). A carcinoma that arises from the lung and is characterized by the presence of malignant glandular epithelial cells. "For example, hsa-miR-1290 has been shown to target SOCS4 and has been associated with heightened proliferation and invasive capacity in lung adenocarcinoma cell lines." (PMID 34072436, 2021). "Distinct miR-944 expression patterns are observed in lung squamous cell carcinoma versus lung adenocarcinoma, and miR-944 modulates malignant phenotypes in NSCLC cells through SOCS4 suppression, thereby promoting oncogenic growth and invasion." (PMID 40657383, 2025).
leukemia (3 papers, 2014 to 2024). A malignant (clonal) hematologic disorder, involving hematopoietic stem cells and characterized by the presence of primitive or atypical myeloid or lymphoid cells in the bone marrow and the blood. "Functional validation using siRNA knockdown in leukemia cell lines showed that knocking down CCDC88A, CTBP2, SOCS4 genes in U937 and K562 cells significantly altered HHT cytotoxicity." (PMID 25628645, 2014). "Taken together, through the initial screening studies in LCLs and further functional validation in leukemia cell lines, we found that the expression of three genes, CCDC88A, CTBP2, and SOCS4, were involved in HHT-induced response." (PMID 25628645, 2014).
viral infection (3 papers, 2014 to 2024). "We had previously shown that SOCS4 restrains viral infection via the hematopoietic compartment, most likely through regulating CD8+ T cell function." (PMID 28195529, 2017). "Given that SOCS proteins play a critical role in regulating immune responses, and expression of SOCS4 in lymphocytes, we investigated the role of SOCS4 in a defined viral infection model in which T cells regulate pathogen clearance." (PMID 24809749, 2014). "However, ablation of the mouse Socs4 gene failed to elicit an overt phenotype, but resulted in increased susceptibility to the pathogenic effects of virus infections, with similar results obtained when the mouse Socs5 gene was ablated." (PMID 39334830, 2024). "The single mammalian SOCS4 has been shown to be broadly expressed, and able to be regulated by EGF stimulation and viral infection at the gene and protein levels, respectively." (PMID 39334830, 2024).
autoimmune disease (1 paper, 2024). A disorder resulting from loss of function or tissue destruction of an organ or multiple organs, arising from humoral or cellular immune responses of the individual to their own tissue constituents. "SOCS4 mutations have been previously indicated in autoimmune disease." (PMID 39676878, 2024).
Autoimmunity (1 paper, 2024). The occurrence of an immune reaction against the organism's own cells or tissues. "A missense mutation in the human SOCS4 gene has been associated with autoimmunity, with Socs4 knockout mice showing altered viral immunity being associated with enhanced inflammation and pathology." (PMID 39334830, 2024). "A SOCS4 mutation was also associated with autoimmunity in a human pedigree." (PMID 39334830, 2024).
benign ovarian neoplasm (1 paper, 2022). "In immunohistochemical study, expression of SOCS4 in EOC was lower than that in benign ovarian neoplasm." (PMID 35723400, 2022). "In the present study, immunohistochemistry revealed that expression of SOCS4 decreased significantly in EOC group (n = 38) compared to benign ovarian neoplasm group (n = 12) (p < 0.001)." (PMID 35723400, 2022). "Decreased expression of SOCS4 was shown in EOC compared to benign ovarian neoplasm." (PMID 35723400, 2022). "Serum exosomal miR-1290 could be considered as a biomarker for differential diagnosis of EOC from benign ovarian neoplasm and SOCS4 might be potential target gene of miR-1290 in EOC." (PMID 35723400, 2022). "Although we did not undertake clinic pathological analysis due to limited patients’ medical information and small sample size, to our knowledge this is first report that showed difference of SOCS4 expression in EOC and benign ovarian neoplasm." (PMID 35723400, 2022). "In benign ovarian neoplasm group, there were no patients with grade 0 or grade 1 SOCS4 expression, while 63% of EOC has grade 0 or grade 1 expression." (PMID 35723400, 2022). "In this study, the expression levels of SOCS4 were examined in EOC and benign ovarian neoplasm." (PMID 35723400, 2022).
diabetes (1 paper, 2016). "Other genes in the SB network related to diabetes are PTP4A2, IQGAP2, and SOCS4." (PMID 26830357, 2016).
hepatocellular carcinoma (1 paper, 2017). A malignant tumor that arises from hepatocytes. "Collectively, these results indicated that miR-500a-3p promotes CSC-like phenotypes of HCC cell via targeting SOCS2, SOCS4 and PTPN11, which further promotes the progression of hepatocellular carcinoma." (PMID 28750679, 2017). "In summary, this study reports that oncogenic miR-500a-3p promotes the CSCs properties and tumourigenicity by negatively regulating SOCS2, SOCS4 and PTPN11, leading to activation of the STAT3 signalling pathway in hepatocellular carcinoma." (PMID 28750679, 2017).
liver cancer (1 paper, 2024). An epithelial or non-epithelial malignant neoplasm that arises from the liver. "Next, we assessed the prognostic value of SOCS family members in HCC, and the results indicated that SOCS2 and SOCS4 are risk‐related genes in patients with liver cancer." (PMID 39307915, 2024). "The study also indicated that SOCS2 and SOCS4 are risk‐related genes for predicting the prognosis of patients with liver cancer." (PMID 39307915, 2024). "SOCS1 alterations through SOCS7 and CISH alterations were detected in liver cancer tissues at the following frequencies: SOCS1, 1.1%; SOCS2, 0.8%; SOCS3, 6%; SOCS4, 0.3%; SOCS5, 1.3%; SOCS6, 1.3%; SOCS7, 2.4%; and CISH, 2.7%." (PMID 39307915, 2024).
lymph node metastasis (1 paper, 2018). "Clinicopathological characteristics analysis showed that SOCS4 expression was negatively associated with higher clinical stage and lymph node metastasis." (PMID 29552286, 2018). "Clinicopathological correlation analysis showed that SOCS4 expression was negatively correlated with higher clinical stage (P = 0.039) and lymph node metastasis (P = 0.025)." (PMID 29552286, 2018).
tumor (13 papers, 2010 to 2025). "To clarify the possible mechanism underlying the pro-tumor effects of miR-1290, we further explored singaling pathway downstream of SOCS4." (PMID 29552286, 2018). "Up-regulation of let-7b is characteristic of prostatic TAMs (Tumor-associated macrophages), which targeting of the SOCS4 3′ untranslated region and inhibition of SOCS4 promoted phosphorylation of STAT3 and STAT6." (PMID 28948005, 2017). "After a median follow up of 10 years, there was a trend for tumours with higher SOCS4 expression levels to be associated with better OS (p = 0.007), and with marginal benefit in DFS although the later remained below statistical significance (p = 0.05)." (PMID 20433750, 2010). "Contrarily, the positive trend of SOCS4 was observed in the lncRNA-LET tumor model, which was consistent with the positive correlation between lncRNA-LET and SOCS4." (PMID 35619921, 2022). "The tumor inhibitory roles of SOCS4 similar to lncRNA-LET were also demonstrated with functional and metabolic assays." (PMID 35619921, 2022). "A total of 439 studies were considered for analysis of SOCS4 expression, among which 13 showed increased expression and 15 showed decreased expression in tumor tissues compared with normal tissues." (PMID 34120621, 2021). "A total of 298 studies were considered for analysis of SOCS4 expression, among which 11 showed increased expression and 2 showed decreased expression in tumor tissues compared with normal tissues." (PMID 34120621, 2021). "We have confirmed that miR-944 has oncogenic function in pathogenesis of SCC, since its dysregulation contributes to cancer cell growth, proliferation and invasion by targeting SOCS4, a tumor suppressor." (PMID 28881596, 2017). "However, little is known about the role of SOCS4 in carcinoma, and their possible influence on tumor growth and malignancy." (PMID 26437444, 2015). "Several studies have suggested a tumor suppressor role for SOCS4." (PMID 24757565, 2014). "In addition, lncRNA-LET could affect miR-106b-5p and miR-93-5p, while SOCS4 affected cell metabolism, thus inhibiting tumor progression." (PMID 35619921, 2022). "Mechanistically, miR-876-5p directly targets the tumor suppressor SOCS4 (Suppressor of cytokine signaling 4), leading to sustained activation of the STAT3 pathway and subsequent upregulation of PD-L1, thereby facilitating tumor immune escape." (PMID 41221298, 2025). "Mechanistically, miR-876 directly targets SOCS4, activating the STAT3 signaling pathway, which subsequently upregulates PD-L1 expression, facilitating tumor immune evasion." (PMID 40140827, 2025). "Less is known about the roles of SOCS4 than about the roles of SOCS2 and SOCS3 in tumor growth and malignancy." (PMID 34120621, 2021). "Unlike the tumor-promoting roles of miR-106b-5p or miR-93-5p, SOCS4 overexpression dramatically inhibited cell proliferation." (PMID 35619921, 2022). "For SOCS4 and SOCS6, only one study reporting increased expression in tumor tissues was identified." (PMID 34120621, 2021). "We hypothesized that SOCS4 might modulate the JAK/STAT3 and PI3K/AKT pathways, therefore serves as a tumor suppressor downstream of miR-1290 in LADC." (PMID 29552286, 2018). "Indeed, in vivo studies have suggested that this may represent a tumor suppressor role, with RUNX1 able to directly repress Socs4 expression leading to increased STAT3 activity, which contributes to tumor development." (PMID 35204004, 2022).